CD7 (CD7 molecule)
Description:
Transmembrane glycoprotein expressed by T-cells and natural killer (NK) cells and their precursors. Plays a costimulatory role in T-cell activation upon binding to its ligand K12/SECTM1. In turn, mediates the production of cytokines such as IL-2. On resting NK-cells, CD7 activation results in a significant induction of interferon-gamma levels.
Synonyms: GP40; LEU-9; TP41; Tp40
Tractability: Antibody: its Gene Ontology location is reachable by antibodies, with high confidence; UniProt predicts a signal peptide or a membrane-spanning region. PROTAC: ubiquitination databases record sites on it; its protein half-life has been measured.
Gene: Protein-coding gene on chromosome 17 (82,313,564 to 82,317,608, reverse strand). Ensembl gene ENSG00000173762.
Subcellular location: Membrane
Gene Ontology:
Molecular function: protein binding; transmembrane signaling receptor activity; signaling receptor activity
Biological process: positive regulation of T cell cytokine production; cell surface receptor protein tyrosine kinase signaling pathway; immune response; T cell activation; adaptive immune response
Cellular component: membrane; plasma membrane
Genetic constraint (gnomAD): Loss-of-function variants: 20 observed, 17.21 expected, observed/expected ratio (o/e) 1.16, 90% interval 0.82 to 1.67. The upper end of that interval is the gene's LOEUF score, 1.67, which puts it in group 6 of 6, group 1 being the genes least tolerant of losing a copy. Missense variants: 291 observed, 295.19 expected, observed/expected ratio (o/e) 0.99, 90% interval 0.89 to 1.09. Synonymous variants: 160 observed, 142.95 expected, observed/expected ratio (o/e) 1.12, 90% interval 0.98 to 1.28.
Homologues: Orthologues: chimpanzee CD7 (97% identical), macaque CD7 (75% identical), dog CD7 (46% identical), mouse Cd7 (45% identical), rat Cd7 (45% identical), zebrafish si:ch211-165d12.4 (21% identical), zebrafish si:rp71-81e14.2 (20% identical), zebrafish si:ch211-188c18.1 (19% identical).
Diseases named in the same sentence as CD7 in open-access papers:
CD7 is named in the same sentence as 142 diseases in open-access papers, as found by Europe PMC text mining. Sharing a sentence is not in itself a finding about the gene and the disease. The quoted sentences say what the papers report.
lymphoma (71 papers, 2010 to 2025). A malignant (clonal) proliferation of B- lymphocytes or T- lymphocytes which involves the lymph nodes, bone marrow and/or extranodal sites. "In this study, ligand-based K12 CAR T cell therapy was investigated for CD7-positive T cell leukemia/lymphoma and AML." (PMID 40589566, 2025). "The expression of T cell antigens, including CD2, CD4, CD5, CD7, and monocytic antigens, has also been reported in B-lymphoblastic leukemia/lymphoma." (PMID 40227608, 2025). "The open-label phase I clinical trial NCT04004637 enrolled patients with r/r CD7-positive T-cell acute lymphoblastic leukemia/lymphoma who underwent transfusion of autologous CD7-targeted CAR-T cells." (PMID 40726984, 2025). "In a phase I trial (NCT04538599) with twelve patients (eleven with T cell leukemia/lymphoma, one with CD7-expressing AML), all met endpoints, with eleven proceeding to efficacy evaluation." (PMID 38816881, 2024). "So far, there have been a few of phase I studies (NCT03081910, NCT04689659, NCT04004637) in regard to the CAR-T cells targeting CD5 or CD7 to treat relapsed/refractory T-lymphocytic leukemia/lymphoma, but with tumor recurrence." (PMID 39462383, 2024). "Another target, CD7, exhibited high expression not only in T lymphoma cells but also in normal T cells." (PMID 38816881, 2024). "Chimeric antigen receptor T cells (CAR T) targeting CD7 for T-cell acute lymphoblastic leukemia/lymphoma (T-ALL/LBL) showed promising efficacy and safety in some clinical trials." (PMID 38745670, 2024). "CD7 is a transmembrane glycoprotein that is highly expressed in more than 95% of lymphoblastic leukemias and lymphomas, and peripheral T-cell lymphoma (PTCL)." (PMID 39620223, 2024). "In NCT02742727, the NK-92 cell line has been engineered to express an anti-CD7 attached to TCR zeta, CD28, and 4-1BB signaling domains and to be infused in patients with CD7-positiveR/R leukemia and lymphoma to evaluate its safety and effectiveness." (PMID 37444456, 2023). "At the 2022 ASH, the PAN team presented an interim report from the Phase II clinical trial of donor-derived CD7 CAR T-cells for the treatment of R/R T-cell acute lymphoblastic leukemia/lymphoma (NCT04689659)." (PMID 37215124, 2023). "CD7 is a transmembrane glycoprotein highly expressed in T-cell lymphoblastic leukemias and lymphomas (>95%), and is also present on the majority of T cells, NK cells, and their precursors." (PMID 37095094, 2023). "So far, there are seventeen phase I/II clinical trials using CAR-T to target CD7 for relapsed/refractory T-cell leukemia/lymphoma/malignancy therapy." (PMID 37108359, 2023). "In a recent study on relapsed or refractory T-cell acute lymphoblastic leukemia/lymphoma patients undergoing anti-CD7 CAR-T therapy, scRNA-seq demonstrated high expression of S100A8 in various T cell subpopulations in the relapsed patients." (PMID 38035111, 2023). "For instance, the application of immunotoxins redirected towards CD7 has been investigated for the treatment of T-cell leukemias and lymphomas." (PMID 35468841, 2022). "The safety and efficacy of allogeneic CD7-redirected CAR-Ts have been investigated in another clinical trial involving patients with R/R T-cell leukemia/lymphoma." (PMID 35468841, 2022). "The expression of CD7 by the lymphoma of the first patient was indeed suggestive for an aggressive form, needing a rapid and more intensive treatment." (PMID 36419498, 2022). "Cytotoxic activity was similarly observed on T cells (CD5+ CD7+) and lymphoma cells (CD5+ CD7‒), as remaining cells had a similar T cell: lymphoma proportion after treatment." (PMID 35158792, 2022). "Currently, only one clinical trial (NCT02742727) related to T-cell malignancies is registered; the purpose of this trial is to evaluate the safety and effectiveness of CD7 CAR-NK92 cell immunotherapy in patients with CD7+ r/r lymphoma and leukemia." (PMID 34422667, 2021).
lymphoma (continued). "CD7 is a TM glycoprotein highly expressed in lymphoblastic T-cell leukemias and lymphomas (>95%) and in a subset of peripheral T-cell lymphomas (PTCL)." (PMID 33081391, 2020). "A significant decrease in the percentage of a subset of regulatory NK cells (CD7+/CD3−/CD56bright/CD16dim/−) was identified in the peripheral blood of lymphoma patients compared to healthy blood donors (p = 0.003)." (PMID 30953461, 2019). "Taken together, this third-generation K12 CAR-T cell has prominent anticancer activity and may be of interest for relapsed/refractory patients with CD7-positive T cell leukemia/lymphoma and AML." (PMID 40589566, 2025). "Taken together, K12 CAR-T cells exhibited better activity in vitro than scFvCD7 CAR-T cells and may hold promise for the treatment of CD7-positive relapsed/refractory T cell leukemia/lymphoma and AML." (PMID 40589566, 2025). "Additionally, to ensure that the ctDNA NGS panel can be used for patients with both myeloma and lymphoma, genes found in non-Hodgkin lymphoma (e.g., CD7) were also included." (PMID 39135074, 2024). "Our previous study showed that CAR‐T cells targeting CD7 may be a promising strategy for T‐lymphoblastic leukemia/lymphoma." (PMID 37039305, 2023). "In addition to CD19, the clinical studies of CAR-NK cells in lymphomas and leukemia have also targeted CD7 (NCT02742727) and CD33 (NCT02944162)." (PMID 36077853, 2022). "For T cell leukemia/lymphoma, CD7 is the most common target, followed by CD30." (PMID 35681646, 2022). "In the past, an anti-CD7 immunotoxin linked by disulfide bonds to Ricin was not effective in a phase I clinical trial with patients with CD7+ T cell leukemia and lymphoma, most probably due to dose-limiting toxicities." (PMID 36430170, 2022). "The NK-92 cell line engineered to express anti-CD33 or anti-CD7 linked to TCR zeta, CD28 and 4-1BB signaling domains are undergoing clinical trials for CD33+ AML (NCT02944162) or CD7+ relapsed or refractory leukemia and lymphoma (NCT02742727), respectively." (PMID 28955340, 2017). "Therefore, K12 CAR T cell therapy might be of use for the treatment of r/r patients with CD7-positive T cell leukemia/lymphoma and acute myeloid leukemia (AML)." (PMID 40589566, 2025). "T-lymphoblastic leukemia/lymphoma is characteristically positive for T cell markers, including cytoplasmic CD3 (which is lineage-defining and specific), CD5, CD7, and CD2, which can all be assessed by flow cytometric analysis." (PMID 40227608, 2025). "In one study, 10.0% of cases of B-lymphoblastic leukemia/lymphoma expressed one or more T cell antigens: CD4 in 5.0% of cases, CD5 in 2.2% of cases, CD7 in 2.2% of cases, and CD2 in 0.6% of cases." (PMID 40227608, 2025). "Based on our analysis, the most likely targets for clinical approval in disease groups such as lymphoma and multiple myeloma are CD20, CD22 (or in combination with CD19), CD38, BAFFR, CD7, and CD5." (PMID 40726984, 2025). "A strategy of sequential CD7 CAR-T therapy and haploidentical hematopoietic stem cell transplantation in 10 patients with relapsed/refractory CD7-positive leukemia or lymphoma yielded encouraging efficacy." (PMID 39149468, 2024). "CD2 is expressed in about 90% adult peripheral T-cell lymphoma and about 70% in pediatric T-acute lymphoblastic leukemia/lymphoma (ALL/LBL) and PTCL, higher than CD7 (40-50%)." (PMID 38711850, 2024). "IHC studies showed the lymphoma cells to be positive for CD3 (8/8, 100%), CD4 (7/8, 87.5%), CD7 (2/3, 66%), and CD30 (20/21, 95%, median expression: 80%)." (PMID 38474383, 2024). "The high expression of CD7 targets in T-cell acute lymphoblastic leukemia (T-ALL) and T-lymphoma has attracted considerable attention from researchers." (PMID 37215124, 2023). "For T-cell malignancies, CAR-T cells targeting T-cell makers, including CD5, CD7, and CD30, are currently being developed and have shown promising responses against T-ALL and lymphoma." (PMID 37798328, 2023).
lymphoma (continued). "CD7 is considered as a key factor in the treatment of T-cell acute lymphoblastic leukemia (T-ALL) and T-lymphoma due to its widespread distribution on tumors." (PMID 37215124, 2023). "We summarized several latest reports on the CAR T cells for the therapy of T cell leukemia /lymphoma from the 2022 ASH Annual Meeting, with latest updates on clinical trials of TvT CAR7, RD-13-01, and CD7 CART." (PMID 36871011, 2023). "Here we launched a phase I trial to explore differences between autologous and allogeneic anti-CD7 CAR-T therapies in T-cell ALL and lymphoma." (PMID 37095094, 2023). "CD7 is uniformly and strongly positive in T-lymphoblastic leukemia/lymphoma (T-ALL) and remains highly expressed during chemotherapy and at relapse, and therefore, CD7 is a promising therapeutic target." (PMID 34944936, 2021). "CD7 is expressed on the cell surface of T cells, and in this trial anti-CD7 CAR-T cells are tested for the treatment of T cell leukemia/lymphoma." (PMID 32775490, 2020). "There was a significant difference in the percentages of regulatory NK cells defined as CD7+/CD3−/CD56bright/CD16dim/− (p = 0.003) between lymphoma patients and controls where the lower percentages of these cells were detected in lymphoma patients." (PMID 30953461, 2019). "After removing CD7 from the cell surface, CD7 CAR T cells expanded and exerted potent anti-leukemic activity in vitro and in vivo against primary CD7+ T-ALL and lymphoma." (PMID 30891427, 2019). "In a recent study to purify adult T-cell leukemia-lymphoma (ATL) cells from acute-type patients by flow cytometry, three subpopulations were observed in a CD3 versus CD7 plot (H: CD3highCD7high; D: CD3dimCD7dim; L: CD3dimCD7low)." (PMID 23349737, 2013). "In lymphoma, lymphocytes are more likely to be large and atypical, and they may lack markers CD2, CD3, CD5, and CD7." (PMID 38899272, 2024). "In two cases, the lymphoma cells expressed CD3, CD7, and Granzyme-B." (PMID 37345080, 2023). "Moreover, a phase I/II trial was conducted to evaluate the safety and efficacy of anti-CD7 CAR-NK cells in CD7+ leukemia and lymphoma patients (NCT02742727)." (PMID 36761751, 2023). "BM flow cytometry gating on the lymphoma cells confirmed the positive expression of CD2, CD3, CD7, CD8, CD56, T‐cell receptor (TCR) alpha‐beta chains, perforin, granzyme B, and negative for CD34, CD4, CD5, and TCR gamma‐delta chains, consistent with natural killer (NK)/T lymphoma involvement." (PMID 37206287, 2023). "Consequently, a robust antitumor activity in preclinical studies against primary CD7+ T-ALL and lymphoma has been observed in preclinical studies." (PMID 33081391, 2020). "We investigated the effects of six small molecule pharmacological agents, which interfere with endocytic and other processes, on SA-mediated augmentation of saporin and saporin-based immunotoxins (ITs) directed against CD7, CD19, CD22 and CD38 on human lymphoma and leukaemia cell lines." (PMID 30791598, 2019). "Pioneering work was done with chemically linked immunotoxins by the group of Stirpe in Bologna and Flavell in Southampton, directing Saporin to human leukemia and lymphoma cells expressing differentiation antigens such as CD2, CD7, CD19 and CD22 on their plasma membrane surface." (PMID 29438358, 2018). "Lymphoma cells usually have the following phenotype: CD2+, CD3+, CD4−, CD5−, CD7+ and CD8−." (PMID 23145171, 2012). "In the context of malignant transformation many lymphomas with a lack of CD7 expression have been described to date." (PMID 20604962, 2010). "Lymphoma cells are usually positive for: CD7, CD3, CD2, CD8, CD56 and negative for CD4, CD5, CD30." (PMID 39317016, 2024). "For instance, TCR-deficient allogeneic T cells expressing anti-CD7 CAR could induce remarkable cytotoxicity against CD7-expressing leukemia and lymphoma cells in vivo without graft versus host disease (GvHD) occurrence." (PMID 35508982, 2022).
lymphoma (continued). "In HSTCL, the lymphoma cells are typically double negative (CD4−CD8−) even if a subset of cases are CD8+, positive for CD3, CD2, CD7, and negative for CD1a and CD5." (PMID 38790955, 2024). "Targeting CD2, therefore, would allow for the effective targeting of a wide variety of CD7 negative or low expression T cell leukemia and lymphomas such as T-ALL, SS, peripheral T cell malignancies, and adult T cell leukemia/lymphoma (ATL)." (PMID 37798328, 2023). "The lymphoma cells were small to medium-sized and resulted as positive, in all patients, for CD3, CD2, CD7, and TIA1 and negative for ALK, CD56, CD57, granzyme-B, and Perforin." (PMID 37345080, 2023). "Lymphoma cells in γδHSTCL showed blast-like morphology and were typically positive for moderate CD2, surface CD3, CD7, and TCRγδ, and weak-to-negative CD5." (PMID 35299754, 2022). "We quantitated the cytotoxic activity in a 1:1 effector-to-target ratio on lymphoma cells (CD5+ CD7‒) from three different patients and found that all CAR constructs were highly effective to eliminate lymphoma cells compared to NK cells not expressing a CAR." (PMID 35158792, 2022). "Negativity for leukocyte common antigen (LCA) and other lymphoid markers (CD3, CD20, CD7, CD4, CD79a, CD30, CD68, PAX5, ALK1, and TdT) rules out malignant lymphoma." (PMID 29914385, 2018). "The pathology report indicated no sign of lymphoma in the left capsule or axillary lymph node; however, the fluid from the area surrounding the left implant showed large atypical cells that were positive for CD30, negative for ALK, and negative for CD2, CD3, CD4, CD7, CD8, CD20, CD56, and TIA-1." (PMID 38256500, 2024). "In contrast, in T-lymphoblastic leukemia/lymphoma, the neoplastic cells may be negative for surface CD3 staining or positive, but variable CD3 is usually not observed, and the expression of pan T cell antigens, including CD2, CD5, and CD7, may be absent, but not variable." (PMID 40227608, 2025).
leukemia (66 papers, 1994 to 2026). A malignant (clonal) hematologic disorder, involving hematopoietic stem cells and characterized by the presence of primitive or atypical myeloid or lymphoid cells in the bone marrow and the blood. "At last we substituted the combination for analysis of dendritic cells and basophils for a combination (CD7/CD56/CD45/CD34) to assess the most frequent leukemia-associated phenotypes." (PMID 25924846, 2015). "In addition, we observed that among the ‘M0-2-like’ leukaemias, a relatively high fraction expressed the CD7 and TdT markers, typically associated with early lymphocyte progenitors and cells of the T-cell lineage, respectively." (PMID 39968161, 2025). "Other candidates include BRINP1 (silenced in some bladder cancers), CD7 (associated with leukaemia), CSTA (encodes a stefin that functions as a cysteine protease inhibitor, suggested as a prognostic tool for cancer), and SUPT20H (a known tumour rejection antigen)." (PMID 32872585, 2020). "The latest study designed a treatment strategy combining CD7‐CAR‐T cells with allogeneic HSC transplantation in 10 patients with relapsed or metastatic CD7+ leukaemia." (PMID 40665579, 2025). "The CD7+CD1a− subset from primary patient samples exclusively responded to proliferation signals and efficiently initiated leukemia in a xenograft mouse model." (PMID 40805157, 2025). "The CAR7 T cells are first made from healthy donor T cells by lentiviral transduction of a CAR that specifically targets CD7 + leukemia cells." (PMID 39256822, 2024). "Overall, this experiment demonstrated the versatility of Val-ILs in targeting and inducing cell death in specific leukemia subtypes by incorporating different antibodies, such as anti-CD7 for T-ALL and anti-CD33 for AML." (PMID 38734740, 2024). "Studies have shown that approximately 30% of patients with AML have CD7 antigen expression on leukemia cells." (PMID 39845313, 2024). "Another pre-clinical study using CAR-T cells targets CD7 expression in leukemia cells by downregulating CD7 expression in CAR-T cells." (PMID 34912707, 2021). "Mice (n = 27) were engrafted with 1 × 107 EGFP+LUC+ labelled Jurkat T cells modified to express either CD3 or CD7, alone or in combination, and 3 days later leukaemia establishment was confirmed by bioluminescent signalling." (PMID 34035409, 2021). "For T-ALL3 case, cells isolated from primary mice re-initiated leukemia with a slight delay for CD7+/CD34− cells compared to CD7+/CD34+ cells in secondary recipient." (PMID 27191650, 2016). "We observed that CD7+/CD34+/− cell fractions from the T-ALL we studied endowed with fast promoting leukemia activity are homogenous in terms of genetics and migration/niche adhesion abilities." (PMID 27191650, 2016). "In T-ALL3 case, the majority of CD7+/CD34+/− derived-cells isolated from BM of primary mice are CD34− and re-initiate leukemia in secondary recipient only with a slight delay for CD7+/CD34− cells compared to CD7+/CD34+ cells." (PMID 27191650, 2016). "As expected, T-ALL6 cells derived from primary recipient re-initiated leukemia in secondary faster than primary transplant with a slight delay for CD7+/CD34− cells compared to CD7+/CD34+ cells." (PMID 27191650, 2016). "These leukemias are immunophenotypically characterized by the aberrant expression of CD7 as well as CD56 (present case and 5 previously reported cases)." (PMID 23877199, 2013). "Tertiary transplant experiments revealed that the human CD45+CD34+CD2+CD7+ population propagated leukemia and seeded hematopoietic niches, which was demonstrative of LIC self-renewal capacity." (PMID 22768113, 2012). "Treatment of SCID/CEM mice with a single IT containing the parental murine IgG1 anti-CD7 or anti-CD38 led to a delay in the development of leukemia, but 90% of animals treated with either IT developed disseminated leukemia cell growth." (PMID 22069735, 2011).